SRFBP1 (serum response factor binding protein 1)
Description:
May be involved in regulating transcriptional activation of cardiac genes during the aging process. May play a role in biosynthesis and/or processing of SLC2A4 in adipose cells (By similarity).
Synonyms: FLJ25286; p49; STRAP; BUD22; Rlb1; p49/STRAP
Tractability: PROTAC: UniProt records ubiquitination sites on it; ubiquitination databases record sites on it; its protein half-life has been measured.
Gene: Protein-coding gene on chromosome 5 (121,961,965 to 122,075,570, forward strand). Ensembl gene ENSG00000151304.
Subcellular location: Cytoplasm, perinuclear region
Subcellular location (Human Protein Atlas): Nucleoli rim
Gene Ontology:
Molecular function: RNA binding
Biological process: maturation of SSU-rRNA
Cellular component: 90S preribosome; nucleus; perinuclear region of cytoplasm
Genetic constraint (gnomAD): Loss-of-function variants: 32 observed, 34.28 expected, observed/expected ratio (o/e) 0.93, 90% interval 0.7 to 1.25. The upper end of that interval is the gene's LOEUF score, 1.25, which puts it in group 5 of 6, group 1 being the genes least tolerant of losing a copy. Missense variants: 530 observed, 440.56 expected, observed/expected ratio (o/e) 1.2, 90% interval 1.12 to 1.29. Synonymous variants: 178 observed, 154.19 expected, observed/expected ratio (o/e) 1.15, 90% interval 1.02 to 1.31.
Homologues: Orthologues: chimpanzee SRFBP1 (98% identical), macaque SRFBP1 (96% identical), pig SRFBP1 (80% identical), rabbit SRFBP1 (77% identical), dog SRFBP1 (76% identical), guinea pig SRFBP1 (76% identical), mouse Srfbp1 (67% identical), rat Srfbp1 (67% identical), tropical clawed frog srfbp1 (42% identical), zebrafish srfbp1 (39% identical), Caenorhabditis elegans F18C12.3 (23% identical).
Diseases named in the same sentence as SRFBP1 in open-access papers:
SRFBP1 is named in the same sentence as 6 diseases in open-access papers, as found by Europe PMC text mining. Sharing a sentence is not in itself a finding about the gene and the disease. The quoted sentences say what the papers report.
dilated cardiomyopathies (1 paper, 2020). "Finally, two more proteins were found to be upregulated upon treatment: sarcoglycan delta (SGCD) and serum response factor binding protein 1 (SRFBP1), usually downregulated or mutated in hypertrophic and dilated cardiomyopathies and during heart failure, respectively." (PMID 32121252, 2020).
glaucoma (1 paper, 2023). Increased pressure in the eyeball due to obstruction of the outflow of aqueous humor. "Prioritized gene variants in our glaucoma case-control cohort supported possible causal roles in four genes for POAG (AQP5, FOXM1, SRFBP1 and CDH6) and three genes in PACG (LAMA2, ACACB and RGL3)." (PMID 36833422, 2023). "Rare, deleterious SNVs in AQP5, SRFBP1, CDH6 and FOXM1 from POAG families and in ACACB, RGL3 and LAMA2 from PACG families were found exclusively in glaucoma cases." (PMID 36833422, 2023). "AQP5, SRFBP1 and CDH6 also revealed significant altered expression in glaucoma in expression datasets." (PMID 36833422, 2023). "We identified rare, possibly pathogenic variations in AQP5, FOXM1, SRFBP1 and ACACB in the sporadic glaucoma cases that were not present in the families." (PMID 36833422, 2023).
Hypertension (1 paper, 2023). The presence of chronic increased pressure in the systemic arterial system. "The likely pathogenic variations in CDH6, SRFBP1 and LAMA2 may assist in disorganization of the ECM components and cytoskeleton, leading to hypertension." (PMID 36833422, 2023).
juvenile open angle glaucoma (1 paper, 2023). Juvenile glaucoma (JG) is a rare autosomal dominant open angle glaucoma, characterized by early onset, severe elevation of intra ocular pressure of rapid progression, leading to optic nerve excavation and, when untreated, substantial visual impairment. "SRFBP1 is located within juvenile open angle glaucoma loci GLC1M on chromosome 5q." (PMID 36833422, 2023).
tumor (1 paper, 2018).
SRFBP1 also shares sentences with these, for which no sentence is quoted: heart failure (1 paper).